GAGE2E (G antigen 2E)
Synonyms: GAGE8; GAGE-12B; GAGE12B
Tractability: Antibody: the Human Protein Atlas places it where antibodies can reach.
Gene: Protein-coding gene on chromosome X (49,341,192 to 49,345,922, forward strand). Ensembl gene ENSG00000275113.
Subcellular location (Human Protein Atlas): Plasma membrane; Cytosol; Golgi apparatus
Homologues: Orthologues: chimpanzee GAGE10 (82% identical). Paralogues in human: GAGE12F (100% identical), GAGE12G (100% identical), GAGE1 (99% identical), GAGE12C (99% identical), GAGE12D (99% identical), GAGE12E (99% identical), GAGE12H (98% identical), GAGE12J (98% identical), GAGE13 (98% identical), GAGE2A (96% identical), GAGE10 (90% identical), PAGE1 (52% identical), and 10 more.
Diseases named in the same sentence as GAGE2E in open-access papers:
GAGE2E is named in the same sentence as 2 diseases in open-access papers, as found by Europe PMC text mining. Sharing a sentence is not in itself a finding about the gene and the disease.
GAGE2E shares sentences with these, for which no sentence is quoted: cancer (2 papers); tumor (1).